MTOR (mechanistic target of rapamycin kinase)
Diseases named in the same sentence as MTOR in open-access papers (continued):
Sharing a sentence is not in itself a finding about the gene and the disease.
cancer (continued). "According to the studies mentioned, SESN2 functions as a tumor suppressor gene in specific cancers, possibly through the AMPK/mTOR signaling pathway." (PMID 40775338, 2025). "FLCN can form a complex with FNIP and perform as a cancer suppressor via regulation of metabolism through AMPK and MTOR." (PMID 40700427, 2025). "This review provides a comprehensive analysis of quercetin's effects on pathways such as PI3K/Akt/mTOR, MAPK/ERK, NF-κB, and JAK/STAT, which are central to cancer cell survival, proliferation, and apoptosis." (PMID 40084006, 2025). "IF, by inhibiting the mTOR pathway and activating AMPK, induces autophagy, which can both limit cancer cell proliferation and enhance the effectiveness of chemotherapy and radiotherapy." (PMID 40429883, 2025). "FTO exerts oncogenic effects on various types of cancer cells, promoting tumor cell growth by activating survival and cell-cycle signaling, such as PI3K/Akt/mTOR pathway, MYC, β-catenin, and CEBPA." (PMID 40234389, 2025). "In contrast, the CUR pre-treatment represents a promising alternative method of therapy designed to boost the CDDP effect specifically ovarian CDDP- resistance SKOV-3/CDDP cancer cell line through induction apoptosis by down-regulating TRXR1, mTOR/STAT3." (PMID 39859517, 2025). "Similarly, nanoparticles targeting the PI3K/Akt pathway with surface-modified PI3K inhibitors (e.g., LY294002) could synergistically block PI3K/Akt signaling, thereby enhancing GA’s inhibition of the PI3K/Akt/mTOR pathway, a pathway frequently dysregulated in malignant tumors." (PMID 41311720, 2025). "Cancer tumors can activate parallel or bypassing signaling pathways, compensating for inhibition of the PI3K/AKT/mTOR axis." (PMID 41157256, 2025). "The target also promotes cancer proliferation, metastasis, or therapeutic resistance through oncogenic signaling pathways including PI3K/AKT/mTOR, VEGF, ERK, and Src pathways." (PMID 40709184, 2025). "Enriched terms such as lysosome organization and chromosome segregation support cancer cell survival and genomic stability, while pathways like PI3K/Akt/mTOR and ATM signaling promote tumor growth and DNA repair." (PMID 40748325, 2025). "All three lymphocyte cell types showed enrichment in pathways strongly involved in immune cell response to cancer, like PD-L1/PD-1 checkpoint, ErbB, MAPK, TNF, PI3K/Akt/mTOR, EGFR, VEGF, NF-kappa B signaling." (PMID 40954493, 2025). "Since this pathway is considered critical in cancer progression, we aim to focus this review on the role of PI3 K/AKT/mTOR signaling pathways in growth, survival, maintenance of BCSCs, and their role in therapeutic resistance." (PMID 40676293, 2025). "Our observation that taxane resistance elevates PI3K-pathway signalling in cancer cells complements the links between taxane sensitisation/resistance and the PI3K/AKT/mTOR pathway." (PMID 40360883, 2025). "In cancer cells, sVASN promoted cell proliferation and migration by upregulating the YAP1/TAZ or mTOR-AKT pathways and it promotes stemness maintenance by regulating Notch1." (PMID 40430053, 2025). "Clinically approved PI3K and mTOR inhibitors, such as Buparlisib, Pictilisib, and Alpelisib, are used for treating cancers, and more inhibitors targeting AKT and dual PI3K/mTOR inhibitors are under clinical trials." (PMID 40573134, 2025). "This provides strong evidence that FFX can regulate mTOR and MYC signaling in cancer cells via activation of the AKT pathway." (PMID 40027648, 2025). "The current section highlights the dual function of autophagy in cancer, adding further complexity to its role through the PI3K/AKT/mTOR pathway." (PMID 40740483, 2025).
cancer (continued). "Particularly in the EMT process of malignant tumours, PI3K/AKT/mTOR signalling is instrumental in promoting tumour anti‐apoptosis and metastasis." (PMID 40665565, 2025). "KEGG analysis showed significant enrichment of differentially expressed genes in cancer-related and drug resistance pathways, including the mitogen-activated protein kinase (MAPK), mammalian target of rapamycin (mTOR), and FoxO signaling pathways." (PMID 40416361, 2025). "In a previous study, pharmacological inhibition of the mTOR pathway using the dual PI3K/mTOR inhibitor LY3023414 induced DNA damage and enhanced CHK1 inhibitor-induced replication stress and cancer cell death in HGSOC models, including OVCAR8 and PEO1 cells." (PMID 40429728, 2025). "Similar regulatory mechanisms have been observed in other cancers, including gastric and lung cancer, suggesting a broader role for miR-34a in cancer progression through modulation of multiple critical signaling pathways, including PI3K/Akt/mTOR." (PMID 40867239, 2025). "The study lacks functional validations of downstream PI3K/AKT regulators (e.g., GSK-3β, mTOR, FOXO proteins) and rescue experiments using AKT activators to further delineate the mechanistic link between PI3K/AKT inhibition and ferroptosis in cancer therapy." (PMID 40732297, 2025). "Our preliminary findings suggest that SESN2 exerts anti-cancer effects in PCa, possibly by inhibiting AMPK phosphorylation, leading to the activation of the mTOR signaling pathway." (PMID 40775338, 2025). "Phenothiazines disrupt critical cancer signaling pathways, including PI3K/Akt/mTOR and MAPK/ERK1/2, to inhibit proliferation, induce apoptosis, and enhance autophagy." (PMID 40718442, 2025). "mTOR, a downstream effector molecule of the PI3K/Akt pathway, is a therapeutic target for various cancers." (PMID 41392241, 2025). "The effective enhancement of radiosensitivity through PI3K/mTOR pathway inhibition and HIF1‐α knockdown highlights the potential of targeting these pathways to overcome radioresistance in cancer treatment." (PMID 40740483, 2025). "The mammalian target of rapamycin (mTOR) pathway is essential for metabolic reprogramming in cancer, and FMRP’s interaction with this pathway points to its potential role in cancer cell metabolism." (PMID 40563420, 2025). "This review specifically focuses on five key signaling pathways: PI3K/Akt/mTOR, NF-κB, Wnt/β-catenin, MAPK/ERK, and STAT3, which play central roles in the mechanisms of cancer resistance." (PMID 40201307, 2025). "In this study, we reported that the ASH1L/HIF-1α complex in invading cancer cells promotes IGF-2 expression, which triggers AKT-GSK3b-mTOR signaling and activates OXPHOS pathways in monocytes in the bone niche." (PMID 40394007, 2025). "Olive oil is involved in the management of these markers to prevent and/or treat all types of cancers by upregulating tumor suppressor genes, downregulating oncogenes, and modulating different pathways (PI3K/AKT/mTOR, Wnt/β‐catenin, and MAPK)." (PMID 40979569, 2025). "ERα is also integral to multiple critical pathways in cancer, including the JAK/STAT, MAPK, PI3K/AKT/mTOR, and Wnt/β-catenin pathways." (PMID 41186627, 2025). "Pathways activated by CXCL12, predominantly in cancer cells, include EMT, hormone ER, PI3K/AKT, RAS/MAPK, RTK, and TSC/mTOR." (PMID 40166682, 2025). "The recognition of the PI3K/AKT/mTOR pathway as a key regulator of hypoxia‐induced EMT and drug resistance in various cancers underscores the importance of targeting this pathway to improve treatment outcomes and overcome therapeutic challenges." (PMID 40740483, 2025). "The PI3K/AKT/mTOR (PAM) signaling pathway is highly conserved in eukaryotes, and it is the pathway that is most often abnormally activated in malignant tumors." (PMID 40170845, 2025). "The “High Signal” list affected 24 cancer drivers, encompassing key genes such as PIK3CA, MTOR, RAF1, and JUN." (PMID 39975128, 2025).
cancer (continued). "The dysregulation of the PI3K/AKT/mTOR pathway in ASCC, driven by IGF2 from CAFs, highlights the potential of IGF2/IGF1R inhibitors as targeted treatments for this rare cancer." (PMID 40740483, 2025). "Quercetin exerts anticancer properties on cancer cells and tumors through the modulation of the PI3K/Akt/mTOR, Wnt/β-catenin and MAPK/ERK1/2 pathways." (PMID 40964670, 2025). "We found that the expression of only TRXR1, mTOR pS2448, STAT3 and STAT3 pS727 proteins in ovarian SKOV-3/CDDP cancer cells treated with CUR followed by CDDP were downregulated, which led to induction of cell death in these cells." (PMID 39859517, 2025). "Quercetin has been shown to inhibit cancer through the modulation of apoptosis and autophagy through the targeting of the PI3K/Akt/mTOR, Wnt/-catenin, and MAPK pathways." (PMID 39863836, 2025). "In addition, ISO significantly down-regulated the expression of phosphorylated PI3K (p-PI3K), phosphorylated Akt (p-Akt), and phosphorylated mTOR (p-mTOR) in two types of cancer cells, revealing a potential mechanism of action by which ISO may act as an inhibitor of the PI3K-Akt-mTOR pathway." (PMID 40507124, 2025). "Specifically, we evaluated the expression of epithelial–mesenchymal transition (EMT) markers, cancer stem cell (CSC) markers, and selected oncogenic mRNAs (RAS, mTOR, and CMYC) in tissue samples from 84 patients." (PMID 40566531, 2025). "In endometrial cancer, miR-99a-5p induces apoptosis and represses cancer cell proliferation and invasion via dual suppression of AKT and mTOR." (PMID 40161350, 2025). "Diphenylureas are utilized to treat cancer by inhibiting cell signaling transduction, such as the RAS-RAF-MEK-ERK signaling pathway and the PI3K-Akt-mTOR pathway." (PMID 40143313, 2025). "Studies have shown that one of the anti-cancer effects of metformin is to change the balance between AMPK activation and mTOR inhibition, resulting in the negative regulation of HIF-1α." (PMID 39944825, 2025). "Our study aligns with these findings, demonstrating that Tempol also targets both AKT/mTOR and ERK proteins, suggesting its potential as a multifaceted anti-cancer agent." (PMID 40729043, 2025). "WikiPathways analysis identified similar critical pathways, including cancer pathways, MAPK signaling, and PI3K AKT mTOR signaling." (PMID 40453371, 2025). "mTOR is an essential regulator of the SASP, and mTOR inhibitors have shown senomorphic effects in senescent cancer cells." (PMID 40896432, 2025). "Inhibits cancer cell proliferation and migration, induces apoptosis via the mitochondrial pathway, blocks PI3K/AKT/mTOR signaling, and promotes cell cycle arrest at the G2/M phase." (PMID 40918117, 2025). "Multiple studies demonstrate that within the realm of cancer, the abnormal activation of PI3K/AKT/mTOR (PAM) signaling promotes tumor survival and proliferation." (PMID 40552278, 2025). "Flavonoids are known to suppress cancer cell growth by inhibiting proliferation and inducing apoptosis through the downregulation of the PI3K/AKT/mTOR/ULK signaling pathway." (PMID 40520175, 2025). "This, in turn, inhibits the PI3K/AKT/mTOR/hypoxia inducible factor‐1 (HIF‐1) pathway and suppresses cancer angiogenesis." (PMID 40717210, 2025). "It has been reported that ATRA affects the growth and proliferation of cancer cells by affecting MAPK, mammalian target of Rapamycin (mTOR) and indirectly phosphatidylinositol-3-kinase (PI3K)/Akt pathways." (PMID 40042556, 2025). "ENO1 is overexpressed in various cancers, and its upregulation drives tumorigenesis and metastasis by modulating the AMPK/mTOR signaling pathway." (PMID 40734168, 2025).
cancer (continued). "The hybrid nanoparticles target tumors effectively, overcoming common drug resistance mechanisms by inhibiting the PI3K/AKT/mTOR pathway, generating ROS, and depleting glutathione (GSH), leading to enhanced cancer cell apoptosis." (PMID 40330466, 2025). "In summary, TMAO exerts a promoting effect in cancer by targeting the VEGF, PI3K, NF-κB, and PERK/Akt/mTOR pathways." (PMID 39948481, 2025). "Leptin stimulates cancer cell growth through JAK2/STAT3 and MAPK signaling, whereas adiponectin counteracts tumor progression by blocking the PI3K/AKT/mTOR pathway via AMPK activation." (PMID 40507982, 2025). "Curcumin disrupts important communication networks inside cells that contribute to cancer development, especially pathways known as PI3K/Akt/mTOR and MAPK/ERK." (PMID 40572668, 2025). "Then, through a comprehensive analysis of the Cancer Cell Line Encyclopedia (CCLE) and Genomics of Drug Sensitivity in Cancer (GDSC) databases, we identified GNE‐317, a PI3K/mTOR inhibitor that crosses the blood‐brain barrier and specifically targets Moesin." (PMID 39921260, 2025). "A. officinalis constituents modulate multiple cancer-related pathways, including ERK1/2, PI3K/AKT/mTOR, and apoptosis signaling, reflecting the effects observed in other medicinal plants such as Zingiber officinale and Astragalus membranaceus." (PMID 40149916, 2025). "Pathway enrichment analysis using the KEGG database revealed that the 31 DEmiRNAs are involved in multiple pathways, including cancer-related signaling, cell cycle regulation, and key transduction cascades such as WNT, MAPK, TGF-β, and mTOR." (PMID 41303548, 2025). "These cancer cells are typically characterized by a quiescent state with suppressed activity of MYC and MTOR." (PMID 41090785, 2025). "Both aging and cancer are marked by dysregulation of key nutrient-sensing pathways, particularly those involving insulin and IGF-1 signaling, mTOR (mechanistic target of rapamycin), and AMPK (AMP-activated protein kinase)." (PMID 40153576, 2025). "PI3K/Akt/mTOR exists at the junction of integrin-mediated ECM–cell interactions and mechanotransduction related to cancer progression." (PMID 40392604, 2025). "In cancer treatment, nanogels deliver siRNA targeting the PI3K/AKT/mTOR pathway to control autophagy and improve results." (PMID 40076496, 2025). "During the proliferating stage of cancer, the cancerous cells undergo various pathways upregulation, such as Fak/PI3K/AKT/mTOR and MAPKs." (PMID 41321380, 2025). "Conversely, in cancer cells, the continuous activation of the PI3K/Akt/mTOR pathway serves as a key driving force for the metabolic adaptability of these cells, contributing to their enhanced survival, proliferation, and invasive capabilities." (PMID 39744225, 2025). "PRGcluster B was also enriched in cancer-related signaling pathways, such as the PI3K/AKT/mTOR pathway and complement pathway." (PMID 41332473, 2025). "VPA has been reported to influence several critical signaling pathways involved in cancer progression, including the PI3K/Akt/mTOR pathway, the Wnt/β-catenin pathway, and the NF-κB pathway." (PMID 40283503, 2025). "Blocking ASCT2 with the inhibitor V9302 reduced cancer cell growth, triggered apoptosis, and suppressed the AKT/mTOR signaling pathway in both in vitro and in vivo models, without causing serious side effects." (PMID 41514527, 2025). "mTOR inhibition resulted in a remarkable decrease in carcinoma formation, supporting that YAP-mediated mTOR activation contributes to tumor initiation." (PMID 39779672, 2025). "This study demonstrated that metformin directly targets carcinoma‐initiating cells in HNSCC, inhibiting tumor progression via mitochondrial complex I inhibition and AMPK/mTOR pathway suppression." (PMID 40387523, 2025). "TQ significantly decreased mRNA levels for PI3K, Akt, and mTOR and increased PTEN gene expression in both cell lines, with similar effects in previous studies on other cancers." (PMID 39769174, 2024).
cancer (continued). "In this scenario, Rottlerin has emerged as a potential agent against cancer: Rottlerin acts as a mitochondrial uncoupler, decreasing the intracellular ATP level and activating AMPK by inhibiting mTOR, thereby regulating autophagic and cell growth pathways." (PMID 38539429, 2024). "Particularly, the key regulators of mTOR signaling such as LAMTOR2, LAMTOR5, YWHAB, LAMTOR1, FKBP1A, and RHEB were also upregulated in the cancer cells of intra‐tumoral TLS‐low group." (PMID 38498682, 2024). "Pathways in cancer refer to signaling cascades crucial to the initiation and development of cancer, encompassing the PI3K/Akt/mTOR, Wnt/β-catenin, and MAPK signaling pathways." (PMID 39310787, 2024). "Signaling pathways play a pivotal role in tumorigenesis and progression in many cancers, such as the JAK/STAT, mTOR and β-catenin pathways, among others." (PMID 38920653, 2024). "The intricate interplay between the AHR and signalling pathways, such as TGF-β, PI3K/AKT/mTOR, NF-κB, FAK/c-Src, and Wnt5a/b-β-catenin, further complicates its role in cancer development." (PMID 39336758, 2024). "The suppression of the Akt/mTOR/c-Myc pathway confers a pharmacological effect of CLs on impeding EMT and CSC, which are drivers of cancer metastasis." (PMID 38672078, 2024). "These cumulative findings demonstrated that the mechanism of action of TMQ was closely related to the activation of transcriptional misregulation in the cancer pathway that inhibited the cholinergic synaptic, AMPK, and PI3K/Akt/mTOR signaling pathways." (PMID 39508039, 2024). "mTOR/TOR signaling, a crucial nutrient-sensing pathway, is upregulated in the progression of multiple types of cancer." (PMID 39261338, 2024). "Lately, some evidences have suggested that various transcription factors, such as JAK2/STAT3, NF-kB, PI3K/AKT/mTOR and MEK1/2/ERK1/2 facilitate the transcription of PD-L1 in cancer." (PMID 38326861, 2024). "Combination therapy inhibits cancer cell viability, PI3K/AkT/mTOR pathway, and tumor-supported autophagic flux but induces apoptotic pathways and altered nuclear genotoxicity profiles." (PMID 39247603, 2024). "Within the mTOR pathway, p70 S6 kinase and PRAS40 act as key modulators of cancer progression, influenced by their phosphorylation status." (PMID 39199311, 2024). "CCL2 produced by omental adipocytes binds to CCR2, activating the PI3K/Akt/mTOR pathway and its downstream effectors HIF-1α and VEGF-A, promoting migration and omental metastasis in cancer cells." (PMID 39408927, 2024). "Abnormal serine/threonine kinase activity has been observed in cancer and it plays an important role in the Akt (protein kinase B) phosphatidylinositol 3-kinase (PI3K)/Akt/mammalian target of the rapamycin (mTOR) signaling pathway." (PMID 39598525, 2024). "The organoid-forming potential of EAC PDOs was increased when treated with Torin-1, an inhibitor of the mammalian target of rapamycin (mTOR), and reduced with mTOR stimulation with MHY1485, suggesting a role for mTOR in regulating stemness of cancer cells." (PMID 38721276, 2024). "Within cancer-related signaling, they significantly inhibited the PI3K/Akt/mTOR/NF-κB, ERK/JNK/p38 MAPK, STAT3, and Hedgehog pathways." (PMID 38841620, 2024). "Activated p-Akt can further activate mTOR and regulate HIF-1α, playing a central role in glycolysis, cancer metabolism, and cancer cell proliferation." (PMID 39741958, 2024). "STAT3 upregulates cancer cell-derived VEGF, and expression of GM-CSF is partially responsible for mTOR signaling." (PMID 38886756, 2024). "KMH-233 is hemocompatible and decreases the protein level of mTOR and NF-κB, while increasing apoptosis in LAT-1-expressing cancer cells." (PMID 38705513, 2024).